ADRA2A (adrenoceptor alpha 2A)
Diseases named in the same sentence as ADRA2A in open-access papers (continued):
Sharing a sentence is not in itself a finding about the gene and the disease.
schizophrenia (8 papers, 2013 to 2023). A major psychotic disorder characterized by abnormalities in the perception or expression of reality. "Regarding ADRA2A epigenetic regulation, both ADRA2A promoter-associated H3K4me3 and H3K27me3 were increased in schizophrenia subjects." (PMID 34930904, 2021). "Association between ADRA2A rs1800544 polymorphism and schizophrenia was found in a study of Czech male patients with schizophrenia." (PMID 32116676, 2019). "The upregulation of ADRA2A expression (encoding α2A-adrenoreceptors) in antipsychotic-treated schizophrenia subjects was related to changes in the histone methylation (increased H3K4me3 and H3K27me3) and acetylation (enhanced H4K16ac) levels at the ADRA2A promoter." (PMID 36979236, 2023). "This enhanced bivalency would mean that schizophrenia subjects show an epigenetic predisposition for ADRA2A mRNA regulation, which might be a specific feature of schizophrenia." (PMID 34930904, 2021). "For ADRA2A promoter region, in schizophrenia subjects, both permissive H3K4me3 (Δ=+105%, p = 0.021) and repressive H3K27me3 (Δ = +86%, p = 0.01) were increased compared to matched controls." (PMID 34930904, 2021). "Actually, at ADRA2A promoter of AP-treated schizophrenia subjects, H3K4me3 and H3K27me3 were both increased over control values, the difference being statistically significant for H3K27me3." (PMID 34930904, 2021). "Considering the specific ADRA2A mRNA increase observed in AP-treated schizophrenia subjects, we aimed to evaluate the effect of acute and chronic antipsychotic treatment in rat brain cortex Adra2a and Adra2c mRNA expression." (PMID 34930904, 2021). "Another important observation was that in AP-treated schizophrenia subjects, permissive H4K16ac at ADRA2A promoter was significantly higher than in matched controls whereas it remained unaltered in AP-free schizophrenia subjects." (PMID 34930904, 2021). "ADRA2A mRNA expression was selectively upregulated in AP-treated schizophrenia subjects (+93%) whereas ADRA2C mRNA expression was upregulated in all schizophrenia subjects (+53%) regardless of antipsychotic treatment." (PMID 34930904, 2021). "In conclusion, epigenetic predisposition differentially modulated ADRA2A and ADRA2C mRNA expression in DLPFC of schizophrenia subjects." (PMID 34930904, 2021). "A recent study on subjects with schizophrenia characterized that a promoter region in ADRA2A, epigenetically modified by both H3K4me3 and H3K27me3, could modulate the expression of ADRA2A in the dorsolateral prefrontal cortex." (PMID 36671430, 2022). "Increased H4K16ac at ADRA2A promoter might be one of the mechanisms tipping the scales in favor of a higher ADRA2A mRNA expression in AP-treated schizophrenia subjects." (PMID 34930904, 2021). "Whether this lack of consistency is due to differences among species or due to a specific antipsychotic-induced modulation of ADRA2A mRNA expression in brains of schizophrenia subjects is unknown." (PMID 34930904, 2021). "Candidate gene studies have not found any association between polymorphisms at ADRA2A/C genes and schizophrenia." (PMID 34930904, 2021). "The unique upregulation of ADRA2A mRNA expression in AP-treated schizophrenia subjects but not in AP-treated rats is likely an outcome of epigenetic predisposition depicted by enhanced bivalent chromatin at ADRA2A promoter." (PMID 34930904, 2021). "Moreover, present observations suggest that ADRA2A mRNA upregulation in AP-treated schizophrenia subjects might be the driving force in the upregulated postsynaptic α2A-adrenoceptor protein expression observed in the same subjects." (PMID 34930904, 2021). "However, levels of H3K4me3 and H3K27me3 at ADRA2A promoter showed a positive correlation in human brain suggesting that these two marks could be concomitantly upregulated in schizophrenia." (PMID 34930904, 2021).
schizophrenia (continued). "The upregulation of ADRA2A expression in AP-treated schizophrenia subjects might be related to observed bivalent chromatin at ADRA2A promoter region in schizophrenia (depicted by increased permissive H3K4me3 and repressive H3K27me3) and could be triggered by the enhanced H4K16ac at ADRA2A promoter." (PMID 34930904, 2021). "The present study aimed to assess the mRNA expression of ADRA2A and ADRA2C in postmortem DLPFC of schizophrenia subjects." (PMID 34930904, 2021). "In this study, we observed a differential ADRA2A and ADRA2C mRNA expression in DLPFC of schizophrenia subjects." (PMID 34930904, 2021). "The results show specific histone PTMs at ADRA2A and ADRA2C promoters in schizophrenia with selective mechanisms in AP-free and AP-treated subjects." (PMID 34930904, 2021). "Additionally, it has been suggested that polymorphisms in ADRA2A (alpha-2A adrenergic receptor), DRD3 (dopamine receptor D3), DBH (dopamine β-hydroxylase) and SNAP-25 (25 kDa synaptosomal-associated protein) are individually or collectively risk factors for schizophrenia." (PMID 25408901, 2013). "Division of schizophrenia subjects by presence or absence of blood antipsychotics, revealed that H3K27me3 at ADRA2A promoter was significantly increased in AP-treated schizophrenia subjects (Δ = +159% vs matched controls, p = 0.006)." (PMID 34930904, 2021). "ADRA2A and ADRA2C mRNA expression in schizophrenia subjects could also be influenced by the fact that most schizophrenia subjects in the study were suicide victims (13 out of 19)." (PMID 34930904, 2021). "Division of schizophrenia group by presence or absence of blood antipsychotics revealed a significant increase in ADRA2A mRNA expression in AP-treated subjects (Δ = +93% vs matched controls, n = 9, p = 0.042)." (PMID 34930904, 2021). "Thus, enriched bivalency at ADRA2A promoter depicted by both H3K4me3 and H3K27me3 enhancement in DLPFC of schizophrenia subjects would render ADRA2A gene poised for transcriptional action." (PMID 34930904, 2021). "In summary, the current study shows ADRA2A and ADRA2C differential regulation in schizophrenia." (PMID 34930904, 2021). "The results showed that neither ADRA2A nor ADRA2C mRNA were altered in depressed suicide victims as opposed to results in the schizophrenia cohort." (PMID 34930904, 2021). "ADRA2A mRNA expression in schizophrenia subjects was not statistically different from that in matched controls (Δ = +25%, n = 19, p = 0.25)." (PMID 34930904, 2021). "Although non-significantly, H3K4me3 at ADRA2A promoter was also increased in AP-treated schizophrenia subjects (Δ = +135% vs matched controls, p = 0.072)." (PMID 34930904, 2021). "On the other hand, the results in both acute and chronically-treated rats failed to explain the upregulation of ADRA2A mRNA expression in AP-treated schizophrenia subjects." (PMID 34930904, 2021). "The aim of this study was to evaluate ADRA2A and ADRA2C gene expression (codifying for α2-adrenoceptor subtypes), and permissive and repressive histone PTMs at gene promoter regions in the DLPFC of subjects with schizophrenia and matched controls (n = 24 pairs)." (PMID 34930904, 2021). "An alternative approach would have been to study ADRA2A and ADRA2C mRNA expression in human brain of subjects treated with antipsychotic drugs but without schizophrenia diagnose." (PMID 34930904, 2021). "ADRA2A mRNA expression was selectively upregulated in AP-treated subjects, whereas ADRA2C mRNA expression was enhanced in schizophrenia subjects regardless of the presence or absence of antipsychotics in blood at the time of death." (PMID 34930904, 2021).
breast carcinoma (6 papers, 2020 to 2024). "Higher expression of ADRA2A was also associated with breast cancer survival and hypothesized to suppress cell proliferation and invasion through the PI3K/AKT/MTOR pathway in cervical cancer." (PMID 38664626, 2024). "Studies have confirmed that the expression of ADRA2A is related to the risk of breast cancer." (PMID 34646329, 2021). "As a tumor suppressor gene, the low expression of ADRA2A directly made the prognosis of breast cancer worse." (PMID 34490040, 2021). "The high expression of LINC01235 leads not only to ESR1 imbalance and drug resistance, but also to abnormal expression of ADRA2A, leading to the deterioration of breast cancer." (PMID 34490040, 2021). "In breast cancer, for patients with luminal tumors, ADRA2A was an independent predictor of DMFS and the only factor that preserves its importance." (PMID 34490040, 2021). "For example, we identified ADRA2A, predicted as oncogene in breast cancer and tumor suppressor in bladder urothelial carcinoma, targeted by 62 compounds." (PMID 31900418, 2020). "In breast cancer, while patients with ADRA2A-high breast cancer showed a favorable prognosis, it may promote metastasis." (PMID 38903083, 2024). "Furthermore, we screened three mRNAs (ESR1, ADRA2A, and DTL) associated with breast cancer drug resistance from key genes." (PMID 34490040, 2021). "The Venn diagram indicated that 2/53 (3.77%) of hub mRNAs (ADRA2A and DTL) were overlapped with breast cancer drug resistance genes." (PMID 34490040, 2021).
Anxiety (5 papers, 2015 to 2026). Intense feelings of nervousness, tension, or panic often arise in response to interpersonal stresses. "Stress, as well as Adra2a antagonists, causes increased norepinephrine in hypothalamus, and anxiety-like behaviour in rats and humans, and can contribute to vulnerability to high alcohol consumption." (PMID 26121187, 2015). "A statistically significant difference was found between the anxiety of being poor scores and ADRA2A rs1800544 genotype." (PMID 40283179, 2025). "Further, early life stress reduces norepinephrine in the amygdala and α2AR (adra2a) gene expression in the hypothalamus, which leads to increased anxiety-like behavior and ethanol drinking, respectively, and enhances ethanol-induced norepinephrine levels in the BLA." (PMID 30322021, 2018).
cervical cancer (5 papers, 2022 to 2024). A primary or metastatic malignant neoplasm involving the cervix. "Overexpressing ADRA2A causes senescence (β-galactosidase staining) in cervical cancer cells by down-regulating PI3K/AKT/mTOR, which is reverted by ADRA2A knockdown." (PMID 36139919, 2022). "Adrenergic receptor proteins alpha 2a (Adra2a) inhibits the activation of PI3K/Akt/mTOR pathway in cervical cancer cells which suggests that there could be a direct relation between adrenergic receptor protein functions and Fib-3." (PMID 35795376, 2022). "Cervical cancers show low alpha2A-adrenergic receptor (ADRA2A) levels and poor prognoses." (PMID 36139919, 2022). "Moreover, ADRA2A overexpression induces antiproliferation, apoptosis, and anti-migration/invasion in cervical cancer cells, accompanied by suppressing PI3K/AKT/mTOR." (PMID 36139919, 2022). "ADRA2A promotes senescence and apoptosis through the inhibition of the PI3K/Akt/mTOR pathway in cervical cancer." (PMID 38903083, 2024).
Abdominal obesity (2 papers, 2009 to 2020). Excessive fat around the stomach and abdomen. "ADRA2A (−1291CG) and other adrenergic receptor SNPs are also involved in metabolism and central obesity." (PMID 33329716, 2020).
asthma (2 papers, 2012 to 2022). "Such architecture of the network indicates that the revealed key nodes are related to four different compartments of the asthma-associated regulome and some of them (Timp1, F5, Ccl12, Ccl6, Ccl9, Adra2a, and Ear1) can be involved in the regulation of similar processes." (PMID 35625754, 2022). "We showed that four genes are genetically associated with asthma or asthma-related phenotypes (the AGC1 gene associated with atopy and atopic asthma, the IFI6, ADRA2A and ADH1B genes associated with asthma)." (PMID 23148572, 2012). "The rs11630178 in the AGC1 gene is associated with atopy (p=0.0003) and atopic asthma (p=0.0001), the rs1247653 located in the IFI6 gene (p=0.019), the rs1119529 in the ADRA2A gene (p=0.009) and the rs13103321 in the ADH1B gene (p=0.002), are associated with asthma." (PMID 23148572, 2012). "Consequently, interactions between physiological factors and emotions may modulate the severity and the symptoms of asthma at least partially through the ADRA2A gene." (PMID 23148572, 2012).
bladder cancer (2 papers, 2020). "High ADRA2A expression was associated with poor overall survival for breast and bladder cancer." (PMID 33042807, 2020). "In conclusion, high expression of ADRA2A, CXCL12, S1PR1, ADAMTS9, F13A1, and SPON1 was associated with poor overall survival in bladder cancer patients, with a P-value <0.05 considered to be statistically significant." (PMID 32239176, 2020).
Cirrhosis (2 papers, 2020 to 2021). A chronic disorder of the liver in which liver tissue becomes scarred and is partially replaced by regenerative nodules and fibrotic tissue resulting in loss of liver function. "The publicly available database from the National Cancer for Biotechnology Information Gene Expression Omnibus (GEO, GSE84044) was used to explore the role of ADRA2A in liver fibrosis/cirrhosis." (PMID 32632241, 2020).
colorectal cancer (2 papers, 2024). A primary or metastatic malignant neoplasm that affects the colon or rectum. "A recent study has shown that ADRA2A agonist highlights cancer immunotherapy, suppressing tumor growth in colorectal cancer and melanoma." (PMID 38903083, 2024).
COVID-19 (2 papers, 2022). A disease caused by infection with severe acute respiratory syndrome coronavirus 2. "Classification using random forest indicated AABs targeting ADRB2, STAB1, and ADRA2A as the strongest classifiers (AABs stratifying patients according to disease outcomes) of post COVID-19 outcomes." (PMID 36238301, 2022).
Insulin resistance (2 papers, 2019 to 2024). Increased resistance towards insulin, that is, diminished effectiveness of insulin in reducing blood glucose levels. "Insulin resistance, a core feature of MetS, is linked to genes such as CDKAL1, ADCY3, and ADRA2A." (PMID 39858569, 2024).
mental disorder (2 papers, 2018 to 2020). A disease that has its basis in the disruption of mental process. "In our results, therapeutic targets or biomarkers of neurological disorder and mental disorder, such as DRD1, DRD2, DRD4, HTR2A, PRL and ADRA2A, were assigned with high scores in both mirtazapine and pramipexole." (PMID 29371651, 2018).
ovarian carcinoma (2 papers, 2023 to 2024). A malignant neoplasm originating from the surface ovarian epithelium. "Activation of ADRA2A promotes the chemosensitivity of carboplatin in ovarian cancer cells." (PMID 38903083, 2024).
pheochromocytoma (2 papers, 2022 to 2024). "Thus, the higher requirement of α-adrenergic receptor blockers in patients with pheochromocytoma harboring the rs553668 polymorphisms of the ADRA2A gene could be due to a lower presynaptic receptor density." (PMID 35453646, 2022).
psoriasis (2 papers, 2013 to 2023). An autoimmune condition characterized by red, well-delineated plaques with silvery scales that are usually on the extensor surfaces and scalp. "To date, only the SNP rs553668 in the ADRA2A gene has been associated with anti-TNF treatment response in psoriasis." (PMID 37631238, 2023). "However, it remains unclear what role ADRA2A plays in the anti-TNF response in psoriasis or psoriasis pathogenesis." (PMID 37631238, 2023).
Sepsis (2 papers, 2024). Sepsis is defined as life-threatening organ dysfunction caused by a dysregulated host response to infection. "Compound 4n represents an important complementary pharmacological tool to studythe involvement of adrenoceptor subtypes in pathophysiologic conditionssuch as inflammation and sepsis and a novel candidate for furtherpreclinical development to treat ADRA2A-mediated pathologies." (PMID 38857067, 2024).
atrial fibrillation (1 paper, 2022). A disorder characterized by an electrocardiographic finding of a supraventricular arrhythmia characterized by the replacement of consistent P waves by rapid oscillations or fibrillatory waves that vary in size, shape and timing and are accompanied by an irregular ventricular response. "In our study, we revealed the association between clinical parameters (age, NIHSS score, atrial fibrillation), as well as SNPs in the PTGS1, ADRA2A, TBXA2R and PEAR1 genes, and laboratory indicators of platelet activity in ischemic stroke patients taking aspirin for secondary stroke prevention." (PMID 36289824, 2022).
diabetic retinopathy (1 paper, 2022). "The association of ADRA2A loci with the risk of advanced diabetic retinopathy in famine-exposed group was further replicated in HKDR." (PMID 35600617, 2022). "Nevertheless, the association of ADRA2A locus with the advanced stages of diabetic retinopathy in famine-exposed individuals in the HKDR was similar to that observed in the DOLCE study reassuring the link between famine-related exposure and elevated risk of severity of diabetic retinopathy." (PMID 35600617, 2022). "In conclusion, a consistent genetic findings on the famine-linked risk of ADRA2A with PDR indicate that the nerves may likely to be responsible for communicating the effects of perinatal exposure to famine on the elevated risk of advanced stages of diabetic retinopathy in adults." (PMID 35600617, 2022).
dyslexia (1 paper, 2023). A learning disorder characterized by an impairment in processing written words. "Furthermore, functional impairment of the norepinephrine system plays a significant role in the pathogenic mechanism of ADHD and dyslexia, with the ADRA2A gene being related to ADHD in a number of studies, as well as ADHD with comorbid dyslexia." (PMID 37667328, 2023).
dyspepsia (1 paper, 2023). An uncomfortable, often painful feeling in the stomach, resulting from impaired digestion. "Fourteen genes corresponding to two gene sets were identified, and the functional dyspepsia-related genes targeted by the activated F. fructus compound were ADRA2A, BDNF, CCK, CRP, GCG, JUN, Kcnh2, PTGS1, PTGS2, Pyy, SLC6A4, and TRPV." (PMID 37375548, 2023).
gastric ulcer (1 paper, 2018). An ulcerated lesion in the mucosal surface of the stomach.
Glucose intolerance (1 paper, 2022). Glucose intolerance (GI) can be defined as dysglycemia that comprises both prediabetes and diabetes. "Researches have shown that overexpression of Adra2a in β cells can lead to impaired insulin secretion and glucose intolerance and increase the risk of T2D." (PMID 36420091, 2022).
Hyperglycemia (1 paper, 2023). An increased concentration of glucose in the blood. "On the other hand, T1AM injection stimulates hyperglycemia and increases plasma glucagon levels in mice, but these effects seem to be rather dependent on the Gi/o coupled Alpha-2A adrenergic receptor (ADRA2A) than TAAR1, which is coupled with coupled Gs." (PMID 38002300, 2023).
Hypoglycemia (1 paper, 2021). A decreased concentration of glucose in the blood. "Sympathetic innervation of islets reciprocally regulates hormone release in response to hypoglycemia by inhibition of insulin release through activation of α2-adrenergic receptors (ADRA2A) on β-cells and stimulation of glucagon secretion by activation of β2-adrenergic receptors (ADRB2) on α-cells." (PMID 33753784, 2021).